DSG2 (desmoglein 2)
Diseases named in the same sentence as DSG2 in open-access papers (continued):
Sharing a sentence is not in itself a finding about the gene and the disease.
cancer (61 papers, 2007 to 2026). A tumor composed of atypical neoplastic, often pleomorphic cells that invade other tissues. "As a member of the cadherin superfamily, DSG2 plays diverse roles in cell adhesion and is implicated in both normal development and cancer progression." (PMID 40607388, 2025). "In contrast, higher Dsg2 expression was associated with progression in cancers of the lungs, the liver, the colon and the skin." (PMID 38671389, 2024). "This is of clinical interest as DSG2 is increasingly implicated in the poor prognosis of patients with cancer." (PMID 38188287, 2023). "Overexpression of DSG2 in human SCC cells is also linked to enhanced cancer cell proliferation and migration (also via activation of c-Src)." (PMID 38188287, 2023). "Within cancer, the ectodomain cleavage of DSG2 has been associated with decreased cell-cell adhesion and decreased cell proliferation." (PMID 38188287, 2023). "In gallbladder carcinoma, loss of DSG2 was associated with cancer progression and resistance to EGFR-targeted therapy through activation of Src kinase." (PMID 38188287, 2023). "Recently, several studies reported that aberrant expression of DSG2 was associated with tumorigenesis and cancer progression in a variety of malignancies." (PMID 35345582, 2022). "Considering that the cancer types were different, we further conducted subgroup analysis to explore the association between DSG2 expression and OS in different cancer types." (PMID 35345582, 2022). "We assessed the association between DSG2 expression and the prognosis of cancers in NSCLC, digestive system cancer and female reproductive system cancer." (PMID 35345582, 2022). "These complicated variables underline the need for more research on the role of DSG2 in different carcinomas and their stages of progression." (PMID 36016457, 2022). "An experiment was conducted to detect LMVD in tissue, which has not been reported in previous studies, and high LMVD was found to be associated with high DSG2 expression, indicating that DSG2 probably increased the lymphangiogenesis of cancer." (PMID 32514251, 2020). "Paradoxically, evidence has emerged that shows an upregulation of some desmosomal components, such as Dsg2, Dsg3 and Pkp3 in cancer, in association with cancer progression and/or reduced survival." (PMID 25629808, 2015). "In addition, Dsg2 and Dsc2 mRNA levels were both negatively associated with individual cancer stages and nodal metastasis status of BC in TCGA database." (PMID 38671389, 2024). "Notably, while proteases that cleave DSG2 have been identified, little is known about how the circulating DSG2 fragments cause progression of cancer, and addressing this requires further research." (PMID 38188287, 2023). "In the present study, although we demonstrated that DSG2 is a useful biomarker for the diagnosis of ESCC and EJA, its sensitivity requires improvement; however, to our knowledge, this is the first report on the diagnostic value of serum DSG2 for early-stage cancer." (PMID 35521959, 2022). "Furthermore, in malignant tumors, results of Dsg-2 revealed severe decrease or loss of membrane expression, which was related to the type of malignancy." (PMID 33372636, 2020). "The work thus suggests sialylated DSG2 as a potential “don't eat me” signal molecule with therapeutic potentials in cancer immunotherapy." (PMID 39813162, 2025). "We therefore, chose three representative cell lines, A549, HeLa, and PANC‐1, for each cancer type and tested the contribution of DSG2 to the trans Siglec‐9 signaling in these cell models." (PMID 39813162, 2025). "These analyses collectively demonstrate that DSG2 is significantly upregulated in multiple carcinoma types and has the potential to serve as a cancer biomarker." (PMID 40615400, 2025). "DSG2 knockdown (KD) impaired the expression of IL-4 and GM-CSF, which both mediate cross-talk between cancer cells and stromal cells in the PCSC niche." (PMID 40615400, 2025).
cancer (continued). "To further clarify the potential prognostic value of DSG2 in cancer, we investigated its expression across cancers via the Sangerbox website." (PMID 40615400, 2025). "Additionally, the virus harbors a deletion in the adenoviral E1B region encoding the E1B-19K protein, enhancing cancer cell apoptosis, and a change in the adenovirus serotype 5 knob to adenovirus serotype 3 knob, facilitating transduction of most solid cancers through desmoglein-2 (DSG2)." (PMID 40465005, 2025). "Patients with high expression of DSG2 have exhibit poor survival outcomes, further supporting its potential as an oncogenic factor in cancer." (PMID 40615400, 2025). "But interestingly, there were different effects of Dsg2 loss on downstream pathways of EGFR activation, malignancy and resistance to EGFR-targeted therapy in these cancers." (PMID 38671389, 2024). "Aberrant expressions of desmoglein 2 (Dsg2) and desmocollin 2(Dsc2), the two most widely distributed desmosomal cadherins, have been found to play various roles in cancer in a context-dependent manner." (PMID 38671389, 2024). "It was reported that deregulation of Dsg2 and its partner Dsc2 contributed to initiation and progression of cancers in a context-dependent manner." (PMID 38671389, 2024). "Based on this, we here aim to investigate the role of DSG2 expression during the initial phase of metastatic spreading and attachment of cancer cells in distant organs and tissue." (PMID 39107343, 2024). "Our data show that expression of DSG2 is relevant for sufficient cell–cell adhesion and formation of larger cancer cell clusters, which are more likely to attach to liver tissue in perfusion experiments." (PMID 39107343, 2024). "Here we discuss the different signaling pathways and cellular functions that are regulated by DSG2 and the impact this has on cancer progression." (PMID 38188287, 2023). "Taking the heterogeneity within individual cancers into consideration, it is evident that the role DSG2 plays in tumorigenesis is complex and context dependent." (PMID 38188287, 2023). "In this article, we review the reported roles of DSG2 in cancer and detail the mechanisms by which DSG2 influences neoplastic behavior." (PMID 38188287, 2023). "Herein, we review the current literature on DSG2 in cancer and detail its impact on biological functions such as cell adhesion, proliferation, migration, invasion, intracellular signaling, extracellular vesicle release and vasculogenic mimicry." (PMID 38188287, 2023). "Taken together, the relationship between DSG2 expression and prognosis in cancer patients is inconclusive and is yet to be systematically reviewed." (PMID 35345582, 2022). "The survival and clinicopathological significance of desmoglein 2 (DSG2) in various cancers is controversial." (PMID 35345582, 2022). "All these studies indicated a differing role for DSG2 in cancer development, progression and response to anticancer therapy, and thus further studies are needed to uncover the mechanisms at play." (PMID 35345582, 2022). "In contrast, other investigations reported DSG2 upregulation in carcinomas, possibly as a barrier to the immune system and drug therapy." (PMID 36016457, 2022). "We used a panel of human carcinoma cell lines that were able to grow as dense spheroids and showed high DSG2 expression (over 80% of cells expressed DSG2) including MDA-MB-231 (breast), Hela (cervix), Huh 7 (liver) and HNC (head and neck) cells." (PMID 36016457, 2022). "This modification improves transduction of cancer cells through desmoglein 2, which is highly expressed by most malignant cells." (PMID 34084172, 2021). "Until now, the role of Dsg2 in cancer progression and its functional mechanisms have been reported to be somewhat different in different cancer types." (PMID 32989241, 2021).
cancer (continued). "To elucidate the molecular mechanism underlying Dsg2 loss-induced progression of GBC, we evaluated the effects of Dsg2 on the signaling pathways involved in cancer cell proliferation, survival, and migration." (PMID 32989241, 2021). "In all the studies, DSG2 has a significant higher expression in cancer tissues than lung normal tissues." (PMID 32095325, 2020). "Ad5 vectors with the chimeric Ad5/3 fiber knob modification, including ONCOS‐102, are thought to use both CD46 and DSG2 to bind to and infect cancer cells." (PMID 31944306, 2020). "Species B Ads pose interesting candidates for oncolytic therapy as their receptors, CD46 and DSG-2, are often upregulated in cancer." (PMID 32957644, 2020). "Increased expression of DSG2 was observed in cancer tissues compared to normal lung tissues (p < 0.001)." (PMID 32095325, 2020). "Junction proteins, such as desmoglein 2 (DSG2) and E-cadherin, have been found to be up-regulated in malignant tumor cells." (PMID 32847045, 2020). "Due to the significance of these proteases in cancer progression and metastasis, we investigated the ability of the matriptase inhibitor kempopeptins C to target the downstream cellular substrates Dsg-2 and CDCP1." (PMID 28926939, 2017). "EnAd infects cells by binding to CD46 and/or desmoglein 2,6 both widely expressed on many carcinoma cells." (PMID 28345021, 2017). "The desmosomal cadherin, desmoglein 2 (Dsg2), is deregulated in a variety of human cancers including those of the skin." (PMID 26918609, 2016). "Desmoglein 2 (Dsg2) is an adhesion protein that is upregulated in many cancers and overexpression of Dsg2 in the epidermis renders mice more susceptible to squamous-derived neoplasia." (PMID 25871385, 2015). "In this report we showed that ectopic expression of Dsg2 in the murine epidermis dramatically altered the expression of many genes involved in cell cycle regulation and cancer development, including the expression of the cysteine protease inhibitor, CSTA." (PMID 25785582, 2015). "The network with the highest significance also contained several cancer-related genes with high expression levels, including DSG2, PRKCA, PLA2G10, and Grp94." (PMID 17726464, 2007). "Importantly, knocking down DSG2 enhances the phagocytosis of different cancer cells to a different extent, indicating the contribution of DSG2 to the overall cell display of Siglec‐9 ligands is cell type‐specific." (PMID 39813162, 2025). "Therefore, our innovative findings suggest that DSG2 is crucial for PC tumorigenesis and the maintenance of stemness, which provides a basis for further research on DSG2 as a potential target for cancer treatment strategies." (PMID 40615400, 2025). "However, little is known about roles of Dsg2 and Dsc2 on tumorigenesis and progression in BC, which is the most common cancer among women." (PMID 38671389, 2024). "Accumulating evidence suggests that DSG2 is dysregulated in human cancers." (PMID 38188287, 2023). "However, additional roles for DSG2 outside of desmosomes are continuing to emerge, particularly in cancer." (PMID 38188287, 2023). "It is tempting to speculate that important similarities may emerge between DSG2-expressing stem cells and DSG2-expressing cancer cells." (PMID 38188287, 2023). "Furthermore, evidence supports a correlation between DSG2 and human papillomavirus (HPV) linked cancers." (PMID 38188287, 2023). "Notably, conflicting roles for DSG2 in cancer progression have emerged and at present appear to coincide with the different cancer types." (PMID 38188287, 2023). "In addition, high DSG2 expression was also reported to promote cancer cell growth and migration, and decrease the response sensitivity to EGFR targeting therapy in NSCLC cancer cells." (PMID 35345582, 2022). "The association between DSG2 expression and prognosis was not consistent between different types of cancers." (PMID 35345582, 2022).
cancer (continued). "DSG2, a key factor that mediates cell-cell junctions, was also reported to regulate cancer cell behavior and could be a biomarker for prognosis in cancer patients." (PMID 35345582, 2022). "DSG2 can be used as a prognostic biomarker for cancer patients." (PMID 33407183, 2021). "However, the role of DSG2-cleaved fragments in cancer and the effect of this hydrolytic expression pattern on HNC progression requires further investigation." (PMID 34203070, 2021). "Is the overexpression of DSG3 in cancer involved in post-translational regulation, such as DSG2?" (PMID 34203070, 2021). "Therefore, cancer cells expressing DSG2 seem to be a good target for treatment with chimeric oncolytic adenoviruses such as ONCOS‐102." (PMID 31944306, 2020). "First, as we found above, DSG2 played a different role in different kinds of cancer." (PMID 32514251, 2020). "Moreover, DSG2 has an impact on the occurrence and development of many tumors and is closely related with diagnosis and prognosis of cancers." (PMID 32095325, 2020). "DSG2 is probably a novel biomarker of cancers but has different functions in different cancers." (PMID 32514251, 2020). "All datasets revealed that DSG2 was upregulated in the cancer group." (PMID 32514251, 2020). "DSG2 was reported to be involved in regulating cell proliferation and tumourigenesis in cancers." (PMID 32300605, 2020). "Previously, we had identified the antagonist role of Dsg2 on cancer metastasis." (PMID 30790141, 2019). "Using these cell lines, we next sought to determine the effect of Dsg2 on cancer cell growth and migration and whether it is mediated through EGFR and c-Src." (PMID 26918609, 2016). "We determined that ectopic expression of Dsg2 activates multiple growth and survival pathways that may promote cancer development and progression." (PMID 25785582, 2015). "Taken together, these data support the notion that Dsg2 may influence cancer development and progression, in part by regulating key signaling pathways that maintain skin homeostasis." (PMID 25871385, 2015). "Previous reports indicate that the receptors for Ad3 are up-regulated on a number of cancer lines, whether these receptors consist of DSG2 or other receptors is unclear." (PMID 26689910, 2015). "Moreover, the OS rates of 25 DSG2-overexpressing cancers were evaluated." (PMID 40615400, 2025). "However, the precise role/s of DSG2 in cancer progression varies across different cancer types." (PMID 38188287, 2023). "Intersecting these cellular advantages via targeting DSG2 in cancer could provide clinical benefit." (PMID 38188287, 2023). "Thus, this study aimed to define the prognostic value of DSG2 in patients with cancer." (PMID 35345582, 2022). "Based on the distinguishing features of JO4 viruses in cancer cell lines with different DSG2 levels, we hypothesized that not only DSG2 binding but also interaction with other molecules or the lack thereof played a crucial role in the life cycle of JO4 viruses." (PMID 36016457, 2022). "Many epithelial cancers are known to highly upregulate the production of DSG2 resulting in formation of a network of cellular “staples” reminiscent of poorly organized junctions that render the tumors resistant to permeation by immune cells and cancer treatments." (PMID 30992466, 2019). "Five of the inherited variants in genes associated with cancer or actionable for hereditary diseases have been described in the literature as pathogenic (MUTYH: c.933+3A > C) or of unknown significance (APC, APOB, DSG2, DSP)." (PMID 30233642, 2018). "Additionally, overexpression of Dsg2 enhances proliferation and migration in cancer cells." (PMID 26918609, 2016). "Therefore, this molecule is discussed as a novel co-therapy for treatment of Dsg2-rich cancers, a concept that might also be applicable for the subset of Dsg2-containing malignant melanomas." (PMID 24558503, 2014).
cancer (continued). "Considering Dsg2 and Dsc2 affected EGFR signaling pathway in some cancers such as cancers of gallbladder, colon, cervix and the lungs, we focused on EGFR phosphorylation and its major downstream AKT and ERK pathways." (PMID 38671389, 2024). "Various epithelial markers including epithelial cell adhesion molecule (EpCAM), cadherin 1 (Cdh1), keratin (Krt) 5/14, desmoglein 2 (Dsg2), and epithelial splicing regulatory protein 1/2 (Esrp1/2) have been adopted to depict the EMT states of cancers." (PMID 37654227, 2023). "In response to EGF ligand stimulation, DSG2 is known to be involved in the activation of EGFR, c-Src and Signal transducer and activator of transcription (STAT3), which supports cancer cell growth and migration." (PMID 38188287, 2023). "Our findings that DSG2 is up-regulated in ESCC and EJA are consistent with reports on other cancers." (PMID 35521959, 2022). "With respect to cancers, depolarization of cells during EMT as well as upregulation in DSG2 expression in tumors relative to normal tissues makes for an attractive target for our molecules." (PMID 30992466, 2019). "Our previous study also showed that Dsg2 antibody and the immunogenic epitope derived from EC2 domain suppress EMT and metastasis of human cancer cell lines." (PMID 30790141, 2019). "We had previously confirmed the Dsg2 antibody and its epitope (named KC21) derived from EC2 domain suppressing epithelial-mesenchymal transition and invasion in human cancer cell lines." (PMID 30790141, 2019). "To further study the ability of Dsg2 to modulate the activation of EGFR and its relevance to cancer, we generated stable A431 SCC cells expressing a GFP-labeled Dsg2 (upper band)." (PMID 26918609, 2016). "Some are supported as important in linking inflammation and cancer, for example PKP2, DSG2 and DSC2." (PMID 26489668, 2015). "For example, a module containing gene DSG2, PKP2 and DSC2, is served as both inflammation and cancer module." (PMID 26489668, 2015). "Desmoglein-2 (DSG2), located on chromosome 18q12.1, is a member of the desmosomal cadherin family, which not only participates in intercellular connectivity and desmosome assembly but also plays an important role in the migration and invasion of cancer cells." (PMID 40615400, 2025). "The anti‐phagocytotic effect of DSG2 was also observed for other cancer cell lines, such as A549 and HeLa, but not as pronounced as for A375." (PMID 39813162, 2025). "To overcome the low expression of the Ad5 binding receptor coxsackievirus and adenovirus receptor (CAR) by cancer cells and improve infectivity, we equipped the virus with an Ad5/Ad3-modified fiber, which allows for CD46 and desmoglein 2 (DSG2) receptor attachment." (PMID 38675909, 2024). "This review explores the canonical and non-canonical functions of DSG2, as well as the context-dependent impacts of DSG2 in the realm of cancer." (PMID 38188287, 2023). "Due to the significance of these proteases in cancer progression and metastasis, as well as their functional redundancy with respect to targeting overlapping substrates, we examined the effect of kempopeptin C on the downstream cellular substrates of matriptase: CDCP1 and desmoglein-2 (Dsg-2)." (PMID 28926939, 2017). "Here we reveal that DSG2 is expressed by non-desmosome-forming human endothelial progenitor cells as well as their mature counterparts [endothelial cells (ECs)] in human tissue from healthy individuals and cancer patients." (PMID 27338829, 2016).